SPP1 (secreted phosphoprotein 1)
Diseases named in the same sentence as SPP1 in open-access papers (continued):
Sharing a sentence is not in itself a finding about the gene and the disease.
esophageal cancer (21 papers, 2008 to 2025). A primary or metastatic malignant neoplasm involving the esophagus. "Our study identified COL3A1, PLAU, and SPP1 as key ECM-associated genes with potential as early diagnostic biomarkers for esophageal cancer." (PMID 41465316, 2025). "The expression levels of COL3A1, PLAU, and SPP1 were significantly higher in esophageal cancer patients compared to healthy controls (p < 0.05 for all three genes)." (PMID 41465316, 2025). "These include SPP1 (osteopontin), SPARC, and POSTN (periostin), all of which have been implicated in esophageal cancer progression." (PMID 40872572, 2025). "Targeting this pathway (for instance, using a FAK inhibitor) was shown to suppress esophageal cancer cell invasiveness, highlighting SPP1’s role in mediating aggressive phenotypes." (PMID 40872572, 2025). "We identified COL3A1, PLAU, and SPP1 as early-stage esophageal cancer markers, highlighting the role of these genes in disease progression." (PMID 41465316, 2025). "SPP1 is a pro-metastatic factor and was identified as a hub gene in an integrative analysis of esophageal carcinoma." (PMID 40872572, 2025). "SPP1 was more likely to be over-expressed in breast, bladder, colorectal, head, neck, liver, lung, and esophageal cancers." (PMID 31849319, 2019). "Analysis of the relationship between SPP1 and the prognosis of various tumors revealed that SPP1 was upregulated in breast, bladder, colorectal, head and neck, liver, lung, and esophageal cancers." (PMID 31849319, 2019). "Together, these mechanisms suggest that COL3A1, PLAU, and SPP1 not only serve as promising biomarkers for early-stage esophageal cancer but also contribute to the pathophysiology of the disease by facilitating key processes such as migration, invasion, and proliferation." (PMID 41465316, 2025). "As a gene that is overexpressed in breast, bladder, colorectal, head and neck, liver, lung, and esophageal cancers, SPP1 has the potential to influence not only the occurrence and progression of LUAD, but also to serve as an independent prognostic marker and a novel therapeutic target." (PMID 35321944, 2022). "A recent study showed that both cell adhesion molecules and ECM components OPN (SPP1) and FN1 might work as biological markers of progression and prognosis in esophageal cancer." (PMID 35252204, 2022). "However, the overexpression of SPP1 was identified in various tumors, including breast, bladder, colorectal, head, neck, liver, lung, and esophageal cancers, and was considered a negative prognostic biomarker." (PMID 37427097, 2023).
kidney damage (21 papers, 2010 to 2025). "We evaluated the expression of kidney damage‐related genes (Havcr1, Lcn2, and Spp1) and found that MHY5396 treatment significantly reduced their expression in the kidneys." (PMID 41159141, 2025). "Therefore, we hypothesized that the increase of SPP1 was proportional to kidney damage in the kidney and urine." (PMID 37696527, 2023).
squamous cell carcinoma (21 papers, 2005 to 2026). A carcinoma arising from squamous epithelial cells. "A recent study reported that CXCL9 and SPP1 are very rarely expressed in the same monocyte, and that the balance of CXCL9+ vs SPP1+ TAMs predict patient outcome for squamous cell carcinomas of the head and neck." (PMID 40176808, 2025). "High-SPP1-expression was noted in 34 patients, 14 men and 20 women, 2 with squamous cell carcinoma, 28 with adenocarcinoma, 1 with adenosquamous carcinoma, and 3 with unknown cancers." (PMID 24758329, 2014). "Low-SPP1-expression was noted in 51 patients, 29 men and 22 women, 11 with squamous cell carcinoma, 39 with adenocarcinoma and 1 with unknown cancer." (PMID 24758329, 2014). "They observed that “SPP1 mRNA, which is barely detectable in normal mouse epidermis, was expressed at moderate-to-high levels in 2 of 3 epidermal papillomas and at consistently high levels in 7 of 7 squamous-cell carcinomas induced by an initiation-promotion regimen”." (PMID 20805891, 2010).
thyroid cancer (21 papers, 2014 to 2025). "In thyroid cancer, the expression levels of SPP1 and CSF1 are significantly up-regulated, while CSF1R inhibitor can reduce their expression, thereby inhibiting tumor cell proliferation." (PMID 37097499, 2023). "Moreover, the level of SPP1 produced by macrophages has been shown to be related to the development of psammoma bodies (PBs) in PTC, which may be linked with the development of thyroid cancer." (PMID 36510497, 2022). "When identifying M1 macrophage-related modules related to the prognosis of thyroid cancer by WGCNA, it was found that the 4-gene signature including SLC11A1 and SPP1 could be used to predict the prognosis of patients with thyroid cancer." (PMID 34631695, 2021). "In addition, qRT-PCR assay performed on a panel of human thyroid carcinomas of different histotypes showed a positive correlation between HMGA1b and SPP1 expression while a negative correlation was observed between CBX7 and the expression of HMGA1b and SPP1." (PMID 25595895, 2015). "Furthermore, a recent study demonstrates that the loss of CBX7 observed in thyroid carcinomas leads to a negative or positive regulation of key genes involved in tumorigenesis, as the AP1 complex members FOS and FOSb, and the chemokine SPP1, respectively." (PMID 25595895, 2015).
diabetic nephropathy (19 papers, 2010 to 2025). "SPP1 encodes osteopontin which has been shown to cause glomerular damage and interstitial fibrosis in diabetic kidney disease." (PMID 35281591, 2022). "A single‐cell sequencing study specifically showed that Spp1 is secreted by injured proximal tubules, podocytes and fibroblasts in a diabetic nephropathy model." (PMID 39911133, 2025). "Recently, SPP1 was proposed to be a hub gene for diabetic kidney disease progression by microarray analysis." (PMID 37906287, 2024). "Some researchers believed that SPP1 could be the core target to treat diabetic kidney disease by using traditional Chinese medicine." (PMID 36387855, 2022). "In this study, we found that changes in a rat model of hypertensive kidney disease, including the expression of iPT cells, SPP1, IL34, and PDGFB, strongly correlated with renal fibrosis in human kidney samples obtained from patients with hypertensive and diabetic kidney disease." (PMID 37906287, 2024).
lymphoma (19 papers, 2012 to 2025). A malignant (clonal) proliferation of B- lymphocytes or T- lymphocytes which involves the lymph nodes, bone marrow and/or extranodal sites. "Dysregulation of the glyco-phosphoprotein osteopontin (OPN)/SPP1 has been implicated in various cancers, including specific types of lymphoma (e.g., large B-cell lymphoma, ALK-positive anaplastic large-cell lymphoma)." (PMID 38275392, 2023). "Screening of RNA-seq data from 100 leukemia/lymphoma cell lines showed elevated expression of SPP1 in HL cell line SUP-HD1, while lower levels were detected in cell lines derived from DLBCL and MCL, confirming our findings in corresponding patients." (PMID 40149711, 2025). "Transcriptomic profiling of these two myeloid clusters revealed an upregulation of chemoattractant SASP factors such as secreted phosphoprotein 1 (Spp1), MHC genes, lysosomal stress markers (Lgals3 and Lgals3bp), and senescence-related genes (Cdkn2a, Cdkn1a, and B cell Lymphoma (Blc2))." (PMID 39200202, 2024). "Wondering whether the over-expression of either sOPN or iOPN in lymphoma cells could affect their behaviour in vivo, we intravenously injected OPL239-IRES-Green, Spp1-IRES-Green and iOPN-IRES-Green cells in sub-lethally irradiated BALB/c mice." (PMID 36503430, 2022).
metabolic syndrome (19 papers, 2014 to 2026). A cluster of metabolic risk factors for CARDIOVASCULAR DISEASES and TYPE 2 DIABETES MELLITUS. "Our analysis identified four essential genes—SPP1, IGF1, CD44, and FLT1—that serve as potential molecular links between Alzheimer’s and metabolic syndrome." (PMID 38809924, 2024). "Consequently, we have identified FLT1, SPP1, CD44, and IGF1 as the critical genes shared among the clusters in the PPI network of AD and metabolic syndrome." (PMID 38809924, 2024).
liver cirrhosis (18 papers, 2015 to 2025). "Our results revealed that there were significantly higher percentages of HBsAg positive status, chronic hepatitis, and liver cirrhosis in S100P-SPP1 + iCCApps than in S100P + SPP1− iCCAphl, further highlighting their distinct pathogenic background." (PMID 35347134, 2022). "In liver cirrhosis, however, trajectory analysis suggested a monocytic origin for Spp1+ macrophages." (PMID 39969512, 2025). "Similarly, in liver cirrhosis, a distinct population of CD9‐positive, TREM2‐positive macrophages, termed scar‐associated macrophages (SAMacs), also exhibits high levels of SPP1 expression." (PMID 40047497, 2025). "Specific loci, including collagen 1A1, secreted phosphoprotein 1, SPRR3 and TNFSF15, have been confirmed to be hypomethylated, resulting in the up-regulation of these genes in patients with liver cirrhosis of various etiologies." (PMID 30038293, 2018).
cardiac hypertrophy (17 papers, 2011 to 2024). "Among the most consistently downregulated genes, HB-EGF and SPP1 have been linked to cardiac hypertrophy by ERK pathway activation." (PMID 35052347, 2021). "The DEGs associated with cardiac hypertrophy were screened via bioinformatics analysis, and eight hub genes were identified, including Akt1, Lox, Timp1, Col1al, Spp1, Ccnd1, Mmp3, and Egfr, which might be a new target for the identification of cardiac hypertrophy." (PMID 36046382, 2022). "Several studies have suggested that Tgfb1 increases ECM protein production and heart hypertrophy in response to Ang II through a mechanism involving Spp1, Serpine1, and Sparc." (PMID 36547406, 2022).
Cerebral ischemia (17 papers, 2015 to 2025). Restriction of arterial blood supply to the brain associated with insufficient oxygenation to support the metabolic requirements of the tissue. "SPP1 is a multifunctional protein which has shown neuroprotective properties in animal models of cerebral ischemia." (PMID 26101539, 2015).
Cognitive impairment (17 papers, 2015 to 2026). Abnormal cognition is characterized by deficits in thinking, reasoning, or remembering. "Microglial Spp1 deficiency exacerbated age‐related memory deficits, whereas its overexpression reversed these cognitive impairments." (PMID 41549460, 2026). "Our study aims to elucidate the contribution of full-length OPN (OPN-FL) plasma expression, OPN N-half, and Spp1 to cognitive impairment in the PIL mice model." (PMID 39684790, 2024). "Other research showed high SPP1 expression in the mild cognitive impairment group compared to the untreated control and dementia groups." (PMID 33276674, 2020). "Intranasal osteopontin (OPN/SPP1) alleviates depression and cognitive deficits after intracerebral hemorrhage in mice." (PMID 41345421, 2025). "In APOE ε4 non-carriers, most of these protein levels were similar to controls, except for inflammation markers SPP1, FABP3 (also in the replication cohort), and GFAP that were higher in more severe stages of cognitive impairment." (PMID 32460813, 2020).
multiple myeloma (17 papers, 2012 to 2023). "And other study identified that SPP1 stimulated multiple myeloma cell proliferation through binding to CD44 and was involved in migration through binding to CD44 or αvβ3." (PMID 32843960, 2020). "Secreted phosphoprotein 1 (SPP1) was also increased in MM-MSCs relative to NBM-MSCs, suggesting that myeloma MSCs may be similar to other types of cancer-associated stromal cells and adipocytes." (PMID 33680918, 2020).
renal fibrosis (17 papers, 2015 to 2026). A final common manifestation of a wide variety of chronic kidney diseases characterized by glomerulosclerosis and tubulointerstitial fibrosis. "Upregulation of SPP1 expression was further confirmed in a mouse renal ischemia-reperfusion model, and this protein is closely associated with renal fibrosis." (PMID 41476974, 2025). "As both Postn and Spp1 are known to drive fibrosis, we aimed to quantify renal fibrosis in histological sections and observed an increased fibrotic area in the renal cortex of mice 28d post-MI compared to sham-operated controls." (PMID 41350805, 2025). "Given that both POSTN and SPP1/OPN are potent drivers of fibrosis, we investigated renal fibrosis 28d post-MI and found a significant increase." (PMID 41350805, 2025). "In vivo gene deletion of SPP1 enhances renal fibrosis via influencing ECM dynamics, substantiating the targeting of SPP1 to impede the advancement of renal fibrosis." (PMID 41293726, 2025). "Nevertheless, the cellular communication between CKD-damaged cells and SPP1 macrophages, as well as the mechanism by which SPP1 macrophages promote renal fibrosis, remain to be elucidated in future studies." (PMID 39691368, 2024). "Previous studies have indicated that exosome-mediated activation of the SPP1/CD44 axis plays a crucial role in renal fibrosis." (PMID 39587675, 2024). "SPP1 hallmarks profibrotic macrophage and drives renal fibrosis." (PMID 37696527, 2023). "SPP1 is considered a major driver for renal fibrosis, the secretion of which is stimulated by inflammatory cytokines and the suppression of which could alleviate kidney fibrosis." (PMID 35309370, 2022).
endometriosis (16 papers, 2013 to 2025). The growth of functional endometrial tissue in anatomic sites outside the uterine body. "SPP1, LIF, TCN1 and CLDN4 were common to adenomyosis and healthy groups of genes, while ANXA2, EDNR8, MMP26, DEPP1, ABCC3, CDA and SLC1A1 were common to endometriosis and healthy groups." (PMID 32933042, 2020). "Furthermore, when compared with healthy control tissue, the proportions of SPP1+ macrophages were consistently increased in cirrhotic/NASH liver, IPF/SSC lung, ICM/DCM heart, keloid/SSC skin, endometriosis uterus, and CKD/AKI kidney." (PMID 37706477, 2023).
Granuloma (16 papers, 2014 to 2026). A compact, organized collection of mature mononuclear phagocytes, which may be but is not necessarily accompanied by accessory features such as necrosis. "Of particular interest are SPP1+ macrophages, which were elevated in TB-diseased lung tissue and strongly associated with the granuloma cuff in our spatial transcriptomics and histology data." (PMID 41489684, 2026). "Bulk gene expression deconvolution of this data supported a significant increase in the frequency of several populations in untreated TB granuloma compared with control LN, including the SPP1+CHI3L1+ macrophage." (PMID 41489684, 2026). "Using the Mycobacterium marinum-zebrafish model, we found that mycobacterial infection induces spp1 expression in macrophages and that spp1 ablation results in granuloma formation defects and reduced survival in adult animals." (PMID 40772762, 2025). "Then, using zebrafish Mycobacterium marinum (M. marinum) granuloma models, we identified an essential role for spp1 in lesion formation and function." (PMID 40772762, 2025). "Differential expression of SPP1 defined a macrophage population that dominated the deconvolved spatial signature of the granulomas we analyzed." (PMID 40772762, 2025). "SPP1 was highly induced in multiple macrophage single-cell clusters and was consistently elevated in the entire myeloid cuff in each of the granulomas we evaluated." (PMID 40772762, 2025). "Finally, Mtb granulomas have more FN1 senescent signaling from endothelial cells but lack MIF and SPP1 signaling for survival compared to MAH granulomas." (PMID 41586350, 2025). "In mice, Spp1 deletion causes granuloma defects in some non-mycobacterial disease states but does not impact protection during M. tb infection in the C57BL/6 mouse model, where organized granulomas do not form." (PMID 40772762, 2025). "To examine potential roles for spp1 in more mature granulomas, we evaluated mycobacterial infection in adult zebrafish, which form more mature and complex caseating granulomas that have shared features with human granulomas." (PMID 40772762, 2025).
ischemia (16 papers, 2018 to 2025). A hypoperfusion of the BLOOD through an organ or tissue caused by a PATHOLOGIC CONSTRICTION or obstruction of its BLOOD VESSELS, or an absence of BLOOD CIRCULATION. "SPP1 (osteopontin), which is expressed in various immune and CNS cells, has shown neuroprotective effects in rat models of ischemia in vivo, by activating the PI3K and P42/44 MAPK pathways." (PMID 39097919, 2024). "A transient early rise in SPARC expression has been linked to both fibroblast migration and effective early extracellular remodeling after ischemia, while SPP1 was found to be essential for effective collagen synthesis preventing LV dilation." (PMID 34895263, 2021). "Though Spp1 was reported to aggravate the dystrophic phenotype, its essential role in recovery from hindlimb ischemia has also been emphasized." (PMID 33925757, 2021). "Interestingly, in an ischemia model, intranasal delivery of a SPP1/OPN peptide suppressed microglial activation and the release of pro-inflammatory cytokines IL-1β and IL-6, an indication of reduced NLRP3 activity." (PMID 38646526, 2024). "One cluster (SAMC; Cd14, Apoe, Spp1, Lpl) was notably mainly present in brain parenchyma after ischemia and absent in the other compartments." (PMID 35177618, 2022).
muscular dystrophy (16 papers, 2008 to 2024). Muscular dystrophy (MD) refers to a group of more than 30 genetic diseases characterized by progressive weakness and degeneration of the skeletal muscles that control movement. "The SPP1 gene, implicated in muscular dystrophy and bone loss, exhibits high expression in TREM2+ lipid-associated macrophages, suggesting its conserved role in age-related characteristics." (PMID 38248779, 2024). "Regarding the functions of TREM2+ Macs in aged individuals, we found that SPP1, which promotes fibrosis in muscular dystrophy and bone destruction, was highly expressed in TREM2+ Macs." (PMID 38088531, 2024). "Previous research has also indicated that SPP1 promotes fibrosis in muscular dystrophy and degradation of the bone matrix responsible for bone loss,22] both of which are recognized as aging phenotypes." (PMID 38088531, 2024). "The Spp1 pathway was further characterized given its known role in promoting muscle fibrosis during muscular dystrophy." (PMID 37418531, 2023). "Gal-3+ macrophages expressed profibrotic factors, including Spp1 and gal-3, and were chronically activated in muscular dystrophy." (PMID 37418531, 2023). "Consistent with a potential role for gal-3+ macrophage–derived Spp1 in the pathogenesis of muscular dystrophy, Spp1 enhances the matrix metalloproteinase 9–mediated processing of TGF-β into its active form to promote muscle fibrosis in mdx mice." (PMID 37418531, 2023). "SPP1 protein is highly expressed in muscle tissues of muscular dystrophy patients, although undetectable in normal muscle." (PMID 31879711, 2019). "SPP1 expression is highly upregulated in affected muscles of humans and animals with muscular dystrophy." (PMID 29065150, 2017). "Spp1 was upregulated in animal models for muscular dystrophy and in human polymyositis and dermatomyositis, and can be regarded as an early marker for muscle inflammation." (PMID 18577208, 2008). "Mouse models of muscular dystrophy in the D2 strain have markedly elevated TGF-β proteins, in part mediated by polymorphisms in the latent TGF-β binding protein 4 (Ltbp4) as well as a feedback loop with osteopontin (Spp1)." (PMID 38175727, 2024). "Given the selective induction of Lgals3 and Spp1 in dystrophic muscle macrophages, we hypothesize that this transcriptional profile defines a fibrogenic macrophage that promotes fibrosis during muscular dystrophy." (PMID 37418531, 2023). "Collectively, these results suggest that the Spp1 pathway is a key regulator of gal-3+ macrophage and FAP interactions during muscular dystrophy and that Spp1 signals primarily through CD44 and a subset of integrin heterodimers to control FAP differentiation." (PMID 37418531, 2023).